RNU6-596P (RNA, U6 small nuclear 596, pseudogene)
Gene: Small nuclear RNA gene on chromosome 8 (57,289,552 to 57,289,649, forward strand). Ensembl gene ENSG00000202265.
Homologues: Orthologues: chimpanzee U6 (100% identical), macaque U6 (96% identical), dog U6 (78% identical), pig U6 (71% identical), rabbit U6 (70% identical), rabbit U6 (65% identical). Paralogues in human: RNU6-1005P (84% identical), RNU6-144P (84% identical), RNU6-480P (84% identical), RNU6-80P (84% identical), RNU6-16P (83% identical), RNU6-21P (83% identical), RNU6-235P (83% identical), RNU6-956P (83% identical), RNU6-1179P (82% identical), RNU6-1207P (82% identical), RNU6-333P (82% identical), RNU6-40P (82% identical), and 1284 more.